ERBB4 (erb-b2 receptor tyrosine kinase 4)
Diseases named in the same sentence as ERBB4 in open-access papers (continued):
Sharing a sentence is not in itself a finding about the gene and the disease.
Obesity (continued). "Here, this work finds that the Nrg4 receptor, ErbB4, is highly expressed in the hypothalamus, and the phosphorylation of hypothalamic ErbB4 is reduced in diet‐induced obesity (DIO) mice." (PMID 37060105, 2023). "ErbB4 deletion in mice fed with a moderate-fat diet leads to the development of metabolic syndrome with obesity, hyperglycemia, insulin resistance and hepatic steatosis." (PMID 34646852, 2021). "Neuroregulin 4 (NRG4), a ligand that specifically binds to ERBB4, has been reported to promote browning of white fat, fuel oxidation, prevention of high-fat diet-induced obesity, and improvement of insulin sensitivity." (PMID 31852448, 2019). "Navigating syntenic regions suggests obesity candidate genes on chromosome 2 that are previously known to be associated with obesity-related diseases: MRPL33, PARD3B, ERBB4, STK39, and ZNF385B." (PMID 23253381, 2012). "Similarly, in individuals with high BMI, the mRNA expression levels of hepatic ERBB4 and NRG4 are reduced, suggesting a protective role for Nrg4-ErbB4 signaling against obesity." (PMID 40243151, 2025). "Peripheral neuregulin-4 stimulated neurons in the paraventricular nucleus of the hypothalamus via ErbB4 while overexpression of ErbB4 in the paraventricular nucleus has a protective effect against obesity, which supports our current hypothesis." (PMID 37373801, 2023). "Collectively, these data indicated that Oxt neuron‐specific knockdown of ErbB4 aggravates obesity." (PMID 37060105, 2023). "Taken together, our data indicate that ErbB4 in the PVH regulates metabolism likely through regulation of OXT expressing neurons, reveal a novel function of ErbB4 and provide insight into pathophysiological mechanisms of depression-associated obesity." (PMID 37669858, 2023). "We then detected the changes of hypothalamic ErbB4 in the diet induced obesity (DIO) mice." (PMID 37060105, 2023). "Emerging evidence suggests that ErbB4 may also be important in the pathogenesis of obesity in humans." (PMID 35220393, 2022). "NRG4 or ErbB4-induced downregulation led to insulin resistance and hepatic steatosis in high-fat diet-fed mice, supporting the importance of NRG4-ErbB4 signalling in the prevention of obesity-associated metabolic disturbances." (PMID 36187779, 2022). "Genetic studies have indicated a link between ERBB4 and type 2 diabetes, and obesity." (PMID 31852448, 2019). "As a novel endocrine factor, circulating Nrg4 may activate the receptor kinases ErbB3 and ErbB4 and coordinate glucose and lipid homeostasis in obesity." (PMID 27772531, 2016). "Importantly, genetic studies have linked ErbB4 with T2DM and obesity." (PMID 40243151, 2025). "Significant associations were observed between morbid obese Han Chinese and CSMD3 (obesity related, IMPC) and ERBB4." (PMID 38483771, 2024). "Taken together, our study reveals the specific cellular mechanisms via which ErbB4 regulates energy balance, highlighting ErbB4 in the PVN as a novel therapeutic target for obesity." (PMID 37060105, 2023). "In TNBC tumors of AA patients with obesity, seventeen miRNAs, seven of which (miR-195-5p, miR-130a-3p, miR-130a-5p, miR-424-5p, miR-148a-3p, miR-374-5p, and miR-30a-5p) potentially downregulated two or more genes (e.g., CLCN4, PLCB1, CDC25B, AEBP2, ERBB4)." (PMID 41009685, 2025). "We found that six genes (Sacm1l, Junb, Bmi1, Erbb4, Dkc1, and Suv39h1) are neuron stress-related genes and increased in the HFD-induced mice obesity model, Bmi1gene was identified as a key genes that can reflect the pathophysiology of obesity." (PMID 39717104, 2024). "Mice lacking ErbB4 developed obesity, dyslipidemia, hepatic steatosis, hyperglycemia, hyperinsulinemia, and insulin resistance." (PMID 32655416, 2020). "Furthermore, a murine model, involving Erbb4 deletion has demonstrated the emergence of various characteristics seen in PCOS patients, specifically disrupted ovulatory cycles with oligomenorrhoea, obesity and impaired oocyte development." (PMID 38408933, 2024).
Obesity (continued). "Finally, high-fat diet females exhibited altered mRNA levels of ERBB4 and NRG1, suggesting that obesity may involve disturbances to mammary gland paracrine circuits that are critical in the control of luminal progenitor function and lactation." (PMID 26926925, 2016). "In this study, the glucose tolerance was also regulated by ErbB4 expressed in Oxt neurons, which may be independent of obesity since we found that glucose tolerance changed considerably when mice were fed a HFD for 4 weeks, in which time the body weight changes slightly." (PMID 37060105, 2023).
depression (23 papers, 2015 to 2026). "Nevertheless, both NRG1 and ERBB4 are among the 269 risk genes identified by genome-wide association study (GWAS) of 246,363 depression patients." (PMID 33990773, 2023). "Accordingly, DA neuron- or VTA-specific deletion of ErbB4 caused a pro-resilient effect in the development of depression-like behaviors." (PMID 33990773, 2023). "A recent GWAS study of 246,363 patients with depression and MAGMA (Multimarker Analysis of GenoMic Annotation) analysis of the aggregated genetic effects identified NRG1 and ErbB4 as putative genes associated with depression." (PMID 33854034, 2021). "Furthermore, Erbb4-deficient mice present mania-like behaviors, including hyperactivity, reduced anxiety and depression, and increased sucrose preference." (PMID 30179154, 2018). "Interestingly, ErbB4 is also a risk gene for major depression disorder." (PMID 37669858, 2023). "Therefore, future studies should explore a possible neuronal function of miR-323 potentially underlying anxiety- and depression-like behaviors and whether miR-323 function is mediated by its target ErbB4." (PMID 33941769, 2021). "Together these observations identify a necessary role of ErbB4 in DA neurons in regulating CSDS-induced depression-like behaviors." (PMID 33990773, 2023). "Together with studies of CKO mice, a parsimonious interpretation of the results is that ErbB4 in VTA DA neurons is necessary for the development of depression-like behaviors." (PMID 33990773, 2023). "Depression-like behaviors were suppressed by mutating or inhibiting ErbB4 in VTA DA neurons, revealing a necessary role of ErbB4 and its activity in depression-like behaviors." (PMID 33990773, 2023). "Moreover, to investigate the potential impact of nNos genetic deletion from Erbb4-positive neurons on anxiety or depression phenotype, we performed the elevated plus maze test and sucrose preference test, respectively." (PMID 38396027, 2024). "Moreover, the function of ERBB4 in dopamine neurons is related to depression-like behaviors, and it regulates the homeostasis of extracellular dopamine and norepinephrine in catecholaminergic cells." (PMID 37491364, 2023). "To investigate the role of ErbB4 in depression-like behaviors, we determined whether its level or activity is changed in the VTA under stress." (PMID 33990773, 2023). "Interestingly, the preference of CSDS-CKO mice was more than that of CSDS-Cre mice, in support of reduced depression-like symptoms by ErbB4 CKO." (PMID 33990773, 2023). "Finally, we showed that acute inhibition of ErbB4 after stress attenuated DA neuron hyperactivity and expression of depression-like behaviors." (PMID 33990773, 2023). "However, both NRG1 and ERBB4 were among the 269 putative genes identified by GWAS of 246,363 depression patients." (PMID 33990773, 2023). "To determine whether ErbB4 kinase activity is required for CSDS-induced depression-like behaviors, we investigated the behavioral changes after ErbB4 inhibition in T796G mice." (PMID 33990773, 2023). "We identified two nodes (depression and rs4672619 mapping to ERBB4 (Erb-B2 receptor tyrosine kinase 4)) that were within the Markov neighborhood of the symptom node in the network and then evaluated the interactive effects of depressive status and rs4672619 genotypes on asthma symptom severity." (PMID 29973587, 2018). "For example, the role of ERBB4 in bipolar disorder and major depression has been widely reported." (PMID 29631039, 2018). "Second, CSDS increased the expression of NRG1 at LDTg; deleting NRG1 in LDTg reduced ErBB4 activation in VTA and CSDS-induced depression-like behaviors." (PMID 33990773, 2023). "We showed that NRG1 in the LDTg was increased by CSDS and was required for ErbB4 activation in VTA DA neurons and depression-like behaviors." (PMID 33990773, 2023).
depression (continued). "Deleting ErbB4 in VTA or in DA neurons, or chemical genetic inhibition of ErbB4 kinase activity in VTA suppressed the development of chronic social defeat stress (CSDS)-induced depression-like behaviors." (PMID 33990773, 2023). "To determine if the ketamine-mediated amelioration of depression-like behaviors depends on NRG1/ErbB4 signaling in PV inhibitory interneurons, we tested the antidepressant effects of ketamine in the FST using mice, by manipulating NRG1/ErbB4 signaling." (PMID 33627623, 2021).
colon carcinoma (22 papers, 2006 to 2024). "Genetically predicted LBD indicated an elevated risk of colon cancer, potentially linked to ERBB4 signaling and lipid metabolism." (PMID 39170445, 2024). "Patients with high ERBB4 expression in colon tumours showed worse survival; both the rs79612564 variant and ERBB4 were proposed as predictive biomarkers of survival." (PMID 35159084, 2022). "Among these target genes, ERBB4 has been reported to be associated with colon cancer metastasis, which was consistent with our results." (PMID 31892859, 2019). "In colon cancer, the mutation of ERBB4 resulted in a loss of differentiation and an activation of the phosphoinositide 3-kinase (PI3K) signalling pathway." (PMID 29133385, 2018). "ERBB4 is overexpressed in human colon cancer associated with enhanced cellular transformation." (PMID 38542474, 2024). "In agreement with this idea, ERBB4 has been related to stem cell function during embryonic developmental processes and in human colon cancer." (PMID 32316671, 2020). "The expression levels of Linc00152 conferred colon cancer cell resistance to oxaliplatin by modulating the miR-193a-3p/ERBB4/AKT signaling axis." (PMID 29523145, 2018). "Linc00152 acting as a ceRNA of miR-193a-3p increases the levels of ERBB4 contributing to oxaliplatin chemosensitivity in colon cancer." (PMID 28108736, 2017). "Enrichment analysis indicated that ERBB4 signaling and lipid metabolism might mediate the causal association between LBD and colon cancer." (PMID 39170445, 2024). "•ERBB4 signaling and lipid metabolism might mediate the causal association between LBD and colon cancer." (PMID 39170445, 2024). "Colocalization and pathway enrichment analysis suggested that LBD and colon cancer possibly shared causal variants (nearby gene APOE), and ERBB4 signaling and lipid metabolism may mediate the causal association between LBD and colon cancer." (PMID 39170445, 2024). "ERBB4 signaling and lipid metabolism may mediate the causal association between LBD and colon cancer." (PMID 39170445, 2024). "In addition, oxaliplatin resistance was conferred in colon cancer through regulation of the Linc00152-miR-193a-3p-ERBB4-AKT pathway." (PMID 29970910, 2018). "ERBB4 is overexpressed in human colon cancer and promotes cellular transformation." (PMID 28629469, 2017). "Moreover, a study on oxaliplatin resistance regulation in colon cancer also revealed that linc00152 is involved in the linc00152/miR-193a-3p/erb-b2 receptor tyrosine kinase 4 (ERBB4) ceRNA signaling axis." (PMID 29156700, 2017). "In addition, the long intergenic noncoding RNA 152 (linc00152) was upregulated and promoted tumor progression and conferred oxaliplatin resistance in colon cancer by functioning as a ceRNA to release erb-b2 receptor tyrosine kinase 4 (ERBB4) by sponging miR-193a-3p." (PMID 31620370, 2019). "Our findings indicated that ERBB4 signaling and lipid metabolism seemed likely to play a role in the LBD-colon cancer pathway." (PMID 39170445, 2024). "The invasiveness and metastasis functions of KITENIN were shown to be mediated by ERK/AP-1 activation through the interaction of KITENIN with Dvl/PKCδ or the KITENIN/ErbB4-Dvl2-c-Jun axis, as an EGFR-independent EGF signal in colon cancer cells." (PMID 25605251, 2015). "In the other colon cancer cell line, mRNA expression of BCL2 and ERBB4 JMa-1 was seen to be upregulated in the presence of WWOX." (PMID 24938873, 2014). "We analyzed the effects of exogenous heregulin on ErbB2, ErbB3 and ErbB4 phosphorylation in Caco-2, DLD-1, and HCT 116 colon cancer cell lines by western blot analysis." (PMID 25416285, 2014). "In vitro and in vivo studies exposed that LINC00152 promotes tumor progression and epithelial-to-mesenchymal transition process in colon cancer and glioblastoma tumors, respectively, trough modulating the LINC00152/miR-193a-3p/ERBB4/AKT signaling pathway and inhibiting miR-107 and miR-16 expression." (PMID 32183133, 2020).
colon carcinoma (continued). "Moreover, Long intergenic non-coding RNA 152 (Linc00152) as a ceRNA can confer oxaliplatin resistance via the Linc00152/miR-193a-3p/ erb-b2 receptor tyrosine kinase 4 (ERBB4)/ serine/threonine kinase 1 (AKT) signaling axis and acts as a prognostic indicator in colon cancer patients." (PMID 28108736, 2017).
renal fibrosis (22 papers, 2018 to 2024). A final common manifestation of a wide variety of chronic kidney diseases characterized by glomerulosclerosis and tubulointerstitial fibrosis. "Notably, ERBB4-IR, a novel long non-coding RNA located on chromosome 1 in the mouse genome, has been implicated in mediating renal fibrosis." (PMID 38768139, 2024). "MALAT1, Erbb4-IR and ASncmtRNA2 cause endothelial cell injury and may involve EndMT-associated renal fibrosis." (PMID 34199672, 2021). "Recently, Erbb4-IR, a lncRNA located within the intron region between the first and second exons of ERBB4 on chromosome 1 of the mouse genome, has been found to induce renal fibrosis and to promote diabetic kidney Injury in db/db Mice by targeting miR-29b." (PMID 38858654, 2024). "A study reported that a novel long non-coding RNA (lncRNA) called Erbb4-IR is accountable for renal fibrosis that is mediated by TGF-β/Smad3, making it a selective therapeutic target for CKD." (PMID 39234105, 2024). "Supporting this, it was also found that by suppressing miR-29b, renal fibrosis was enhanced in T2DN by Erbb4-IR through a Smad3-dependent lncRNA." (PMID 39234105, 2024). "We also find that specifically targeting Erbb4-IR can inhibit renal fibrosis in mouse models of obstructive and diabetic nephropathy." (PMID 37449045, 2023). "Of them, the lncRNA Erbb4-IR is a novel Smad3-dependent lncRNA that mediates renal fibrosis in obstructive and diabetic nephropathy." (PMID 37449045, 2023). "Upregulation of TGF-β/Smad-mediated Erbb4-IR and LRNA9884 were observed in renal fibrosis, as they up-regulate the pathogenic effectors via transcriptional regulation at genomic level." (PMID 34299192, 2021). "Kidney-targeted silencing of Erbb4-IR reduces albuminuria, serum creatinine, and renal fibrosis in db/db mice." (PMID 34360646, 2021). "Erbb4-IR is a novel lncRNA responsible for TGF-β1/Smad3-mediated renal fibrosis and it is a specific therapeutic target for chronic kidney disease (CKD)." (PMID 32295041, 2020). "Our previous studies demonstrated that lncRNA (Erbb4-IR) induced renal fibrosis via Smad3-Smad7 pathway in the mouse UUO-induced kidneys, nevertheless, under diabetic conditions Erbb4-IR improved renal inflammation via miR-29b." (PMID 33192605, 2020). "This study also identified Erbb4-IR as responsible for TGF-β/Smad3-mediated renal fibrosis by downregulating Smad7." (PMID 32295041, 2020). "For example, lncRNA Erbb4-IR was found to promote renal fibrosis by targeting miR-29b while other studies demonstrated that inhibition of Linc00963 and H19 were protective against renal fibrosis." (PMID 30914951, 2019). "Our group showed that silencing of Erbb4-IR in the kidney, using a non-invasive ultrasound microbubble-mediated technique, significantly improved renal function and inhibited renal fibrosis in both diabetic and UUO-injured mice." (PMID 30287731, 2018). "We thus examined whether treatment with SIS3 inhibits renal fibrosis in T2DN via a Smad3-dependent Erbb4-IR mechanism." (PMID 38164169, 2024). "In the present study, we also revealed that inhibition of Erbb4-IR-mediated renal fibrosis and LRNA9884-dependent inflammation may be another mechanism by which preventive treatment with AAGN protected against T2DN." (PMID 36147472, 2022). "MALAT1, Erbb4-IR, and ASNCMTRNA2 cause EC injury and may be involved in EndMT-related renal fibrosis." (PMID 36299256, 2022). "Therefore, Erbb4-IR functions as a trans-regulator to negatively regulate miR-29b and Smad7 in renal fibrosis." (PMID 34360646, 2021). "Similarly, lncRNA ERBB4-IR is involved in the development of renal fibrosis in diabetes and its silencing in diabetic mice protects against albuminuria and fibrogenic processes." (PMID 34199672, 2021). "Erbb4-IR binds to the inhibitory Smad7 and blocks TGF-β/Smad3-induced renal fibrosis, while overexpression of Erbb4-IR may promote fibrosis by downregulating the expression of Smad7." (PMID 34054586, 2021).
renal fibrosis (continued). "Similarly, a very interesting study demonstrated the role of lncRNA ERBB4-IR in renal fibrosis and its silencing protected the rat models from high albuminuria and inhibiting the development of DN." (PMID 34742256, 2021). "Similarly, lncRNA ERBB4-IR also promotes renal fibrosis via the activation of the TGFB/SMAD3 pathway." (PMID 32194418, 2020). "Interestingly, knockdown of this lncRNA ERBB4-IR in DN mice protected the mice from having high albuminuria and creatinine, as well as prevented renal fibrosis." (PMID 32194418, 2020). "Among them, we demonstrated that targeting Erbb4-IR may represent a novel therapy for inhibiting progression of renal fibrosis, whereas Arid-IR may related to the renal inflammation." (PMID 33192605, 2020). "Therefore, renal fibrosis and renal dysfunction are largely promoted by Erbb4-IR during the progression of T2DN." (PMID 30891461, 2019). "Furthermore, we also identified that blockade of lncRNA Erbb4-IR could be another mechanism through which SIS3 treatment inhibited renal fibrosis in T2DN." (PMID 38164169, 2024). "Thus, inhibition of Erbb4-IR may be another mechanism by which treatment with SIS3 suppressed renal fibrosis in T2DN." (PMID 38164169, 2024). "Erbb4-IR correlates negatively with SMAD7 expression and either inhibits or promotes TGF-β/Smad3-mediated renal fibrosis in vivo and in vitro." (PMID 34059951, 2021). "Silencing Erbb4-IR was shown in vitro to block TGF-β1-induced collagen I and α-SMA expressions, and effectively attenuate renal fibrosis by inhibiting TGF-β1/Smad3 signaling." (PMID 32295041, 2020). "Another example is ErbB4-immunoreactivity (Erbb4-IR), which is a novel lncRNA that contributes to TGF-β/Smad3-mediated renal fibrosis and a potential therapeutic target for chronic fibrotic kidney disease." (PMID 31281667, 2019). "In addition, Erbb4-IR can also target Smad7, and specific silencing of Erbb4-IR expression up-regulates Smad7 in the kidneys, thereby attenuating TGF-β1/Smad3-induced renal fibrosis in vivo and in vitro." (PMID 36299256, 2022). "The functional role of Erbb4-IR in T2DN is revealed by kidney-specific silencing of Erbb4-IR to protect against the development of T2DN such as elevated microalbuminuria, serum creatinine, and progressive renal fibrosis in db/db mice." (PMID 30891461, 2019).